CROCC2 (ciliary rootlet coiled-coil, rootletin family member 2)
Tractability: No criterion of Open Targets' tractability assessment is met for any kind of drug.
Gene: Protein-coding gene on chromosome 2 (240,906,330 to 240,993,311, forward strand). Ensembl gene ENSG00000226321.
Gene Ontology:
Cellular component: centriole; centrosome
Genetic constraint (gnomAD): Loss-of-function variants: 129 observed, 123 expected, observed/expected ratio (o/e) 1.05, 90% interval 0.91 to 1.21. The upper end of that interval is the gene's LOEUF score, 1.21, which puts it in group 5 of 6, group 1 being the genes least tolerant of losing a copy. Missense variants: 1,394 observed, 1,319.3 expected, observed/expected ratio (o/e) 1.06, 90% interval 1.01 to 1.1. Synonymous variants: 645 observed, 570.53 expected, observed/expected ratio (o/e) 1.13, 90% interval 1.06 to 1.21.
Homologues: Orthologues: chimpanzee CROCC2 (98% identical), macaque CROCC2 (91% identical), rat Crocc2 (65% identical), mouse Crocc2 (63% identical), pig CROCC2 (59% identical), guinea pig CROCC2 (53% identical), tropical clawed frog crocc2 (37% identical). Paralogues in human: CROCC (39% identical), CEP250 (24% identical), CEP135 (11% identical), TSGA10 (6% identical).
Diseases named in the same sentence as CROCC2 in open-access papers:
CROCC2 is named in the same sentence as 1 disease in open-access papers, as found by Europe PMC text mining. Sharing a sentence is not in itself a finding about the gene and the disease. The quoted sentences say what the papers report.
ovarian carcinoma (1 paper, 2021). A malignant neoplasm originating from the surface ovarian epithelium. "Further studies should focus on the biological function of CROCC2 on the prognosis of ovarian cancer." (PMID 34149794, 2021).